BMI1 (BMI1 proto-oncogene, polycomb ring finger)
Diseases named in the same sentence as BMI1 in open-access papers (continued):
Sharing a sentence is not in itself a finding about the gene and the disease.
gastric cancer (continued). "In conclusion, our findings demonstrated that circDONSON promoted cisplatin resistance in gastric cancer cells by regulating miR-802/BMI1 axis, highlighting a potential therapeutic target to overcome chemoresistance in gastric cancer patients." (PMID 32581651, 2020). "In gastric cancer, the co-expression of USP22 and BMI1 was shown to be associated with shorter disease-free survival and a poor prognosis for overall survival." (PMID 34660907, 2020). "The association between Bmi-1, RKIP and the clinical outcome of gastric cancer has been reported in our previous study." (PMID 32580736, 2020). "Targeting BMI1+ CSCs has been shown to overcome chemoresistance and inhibit metastases in squamous cell carcinoma and gastric cancer." (PMID 32005118, 2020). "Our findings demonstrated circDONSON promoted cisplatin resistance in gastric cancer cells by regulating miR-802/BMI1 axis, shedding light on the development of a novel therapeutic strategy to overcome chemoresistance in gastric cancer patients." (PMID 32581651, 2020). "The mRNA expression of HOXA11 was positively correlated with the expression level of CD133 (R=0.13, P=0.014) and Bmi1 (R=0.16, P=0.0023) in gastric cancer tissues of TCGA database." (PMID 31695791, 2019). "For example, it promotes cell proliferation, migration, and invasion in gastric cancer by targeting Bmi1 and miR-219-1." (PMID 31310241, 2019). "Overall, our results show that miR-128 can inhibit gastric cancer migration, invasion, proliferation, and metastasis by targeting Bmi-1 in vivo and in vitro." (PMID 28424413, 2017). "To further understand the function and role of miR-128, we used prediction tools and luciferase reporter assays to search for the direct downstream gene of miR-128 in gastric cancer cells, and we found the gene to be Bmi-1." (PMID 28424413, 2017). "We also found that Bmi-1(B cell-specific Moloney murine leukemia virus integration site 1) and TGFβR1 expression were significantly decreased in miR-128 high-expressing gastric cancer cell lines, whereas the expression of other genes was unchanged." (PMID 28424413, 2017). "In this study, miR-34a is reported to inhibit Bmi-1 by targeting c-Myc in gastric cancer cells, resulting in a PTEN-dependent reduction of phospho-AKT." (PMID 28100259, 2017). "To further analyze the relationship between Bmi-1 and miR-128, we examined the expression of Bmi-1 in 135 gastric cancer tissues and adjacent normal mucosal tissues by western blot." (PMID 28424413, 2017). "Taken together, our study demonstrates that USP22 is indispensable for gastric cancer stem cell self-renewal through stabilization of BMI1." (PMID 28415621, 2017). "In GC, co-expression of USP22 and BMI1 was prognostic for gastric cancer progression and treatment failure." (PMID 28415621, 2017). "It is also known that polycomb gene with tumor suppressor activity MEL-18 down regulates BMI1 expression in breast and gastric carcinoma." (PMID 28445986, 2017). "CSCs are thought to sustain metastasis and chemoresistance, and we also found that Bmi-1 knockdown by Ad-Bmi-1i sensitized gastric cancer cells to chemotherapy and deceased cell migration ability." (PMID 27009837, 2016). "Firstly, we compared the Bmi-1 silencing efficiency for GES-1 (normal immortal gastric mucosal cells) and gastric cancer cells with different Bmi-1 expression levels." (PMID 27009837, 2016). "As we found Bmi-1 upregulates miR-34a in gastric cancer cells, here, we explored the function of miR-34a in gastric cancer." (PMID 27644439, 2016). "Functional studies revealed that ectopic expression of miR-15a decreased Bmi-1 in gastric cancer cell lines with reduced proliferation and tumor invasion." (PMID 26894855, 2016). "In this study, we systematically investigated the functional roles of miRNA mediated Bmi-1 suppression in gastric cancer." (PMID 26894855, 2016).
gastric cancer (continued). "In this study, we engineered a AAV vector to deliver Bmi-1 shRNA driven by its own promoter to treat gastric cancer in vitro and in vivo." (PMID 27009837, 2016). "To ensure that such inhibition of gastric cancer cell proliferation is directly due to the reduction of Bmi-1, we were able to reverse the miR-15a suppressed proliferation by restoration of Bmi-1 expression." (PMID 26894855, 2016). "In this study, we intended to explore the role and mechanisms of Bmi-1 in regulating stem cell-like features of gastric cancer." (PMID 27644439, 2016). "So we used serum-free culture microsphere formation to measure the self-renewal ability of stem-like cells, and our results revealed that Bmi-1 overexpression promotes the self-renewal ability of gastric cancer cells." (PMID 27009837, 2016). "We next analyzed the relationship between Bmi-1 expression and gastric cancer patients' survival based on 352 clinical samples." (PMID 26894855, 2016). "Our results suggest that there is a good possibility that a relative large number of patients retained a significantly high enough level of miR-15a to suppress the expression of Bmi-1 in gastric cancer." (PMID 26894855, 2016). "In contrast, gastric cancer cells with high levels of Bmi-1 proliferate rapidly, making them sensitive to chemotherapy." (PMID 26894855, 2016). "Our results support the important roles of Bmi-1 played in tumor invasion and growth in gastric cancer with a unique regulatory mechanism by miR-15a." (PMID 26894855, 2016). "In order to further verify the relationship between Bmi-1 and miRNAs, we used QRT-PCR method to detect Bmi-1 mRNA and miR-21, miR-34a levels in the gastric cancer tissues, and corresponding normal gastric mucosa tissues from 74 patients with gastric cancer." (PMID 27644439, 2016). "CCK-8 method was used to detect the influence of Bmi-1 on chemotherapy sensitivity of gastric cancer cells, and Transwell Chambers as an in vitro migration model were used to detect the effects of Bmi-1 on the migration ability of gastric cancer cells." (PMID 27644439, 2016). "The prognostic significance of Bmi-1 in gastric cancer supports future multi-center large cohort studies." (PMID 26894855, 2016). "Cellular senescence constitutes a powerful barrier to carcinogenesis, and our previous studies showed that knockdown of Bmi-1 by Bmi-1 shRNA can induce cellular senescence in gastric cancer cells." (PMID 27009837, 2016). "The protein expression of Bmi-1 and miR-15a RNA levels was inversely correlated (P = 0.034, R2 = 0.22, r = −0.48) based on two-tailed Spearman correlation in the gastric cancer patient samples." (PMID 26894855, 2016). "Serum-free suspension culture method was used to detect microsphere formation rate of gastric cancer cells after changing Bmi-1 expression." (PMID 27644439, 2016). "This is consistent with our observation that knock-down Bmi-1 expression by miR-15a reduces gastric cancer cell proliferation." (PMID 26894855, 2016). "The median survival time for gastric cancer patients demonstrating high expression of Bmi-1 was significantly (P < 0.024) shorter (24.5 months) in comparison to patients with low Bmi-1 expression (43.5 months)." (PMID 26894855, 2016). "We found that expression of Bmi-1 was increased whereas phospho-AMPK was decreased in gastric cancer and lung adenocarcinoma specimens." (PMID 26717043, 2016). "Bmi-1 positively regulates stem cell-like properties of gastric cancer and upregulates miR-21 and miR-34a." (PMID 27644439, 2016). "Our results show that the expression of miR-15a is significantly reduced in gastric cancer and the protein expression levels of Bmi-1 are inversely correlated with miR-15a (P = 0.034) in gastric cancer patient samples." (PMID 26894855, 2016). "Furtherly, we explored the cytotoxicity of Ad-Bmi-1i detected by Cell Counting Kit (CCK-8) assay, and showed that less toxicity was found for GES-1 cells compared with gastric cancer with higher Bmi-1 expression." (PMID 27009837, 2016).
gastric cancer (continued). "To explore the correlation between AMPK and Bmi-1, we collected 66 paraffin-embedded gastric cancer specimens and 65 lung adenocarcinoma specimens from the Department of Pathology, the First Affiliated Hospital of Nanchang University." (PMID 26717043, 2016). "First, our data revealed that, as compared to adjacent normal tissue, Bmi-1 was highly expressed in gastric cancer, whereas phosphorylation of AMPK (p-AMPK) was reduced." (PMID 26717043, 2016). "We also detected the expression of stem cell markers including Oct-4, Sox-2, Glil, CD44, and CD133 in the primary sites of gastric cancer and analyzed the correlation between these stem cell markers and Bmi-1 by spearman rank correlation test." (PMID 27644439, 2016). "Silencing Bmi-1 specifically in Bmi-1 highly-expressed gastric cancer cells was expected to achieve the inhibition of the malignant and stem cell-like phenotypes." (PMID 27009837, 2016). "In the present study, Bmi-1 was found to be significantly overexpressed in the gastric cancer tissues and cell lines compared with the adjacent normal tissues and GES-1 normal gastric epithelial cells, respectively." (PMID 25295122, 2014). "In conclusion, miR-183 is downregulated in gastric cancer cells and tissues, and inhibits gastric cancer cell proliferation and invasion by targeting Bmi-1." (PMID 25295122, 2014). "Bmi-1 was also confirmed as a downstream target of miR-183 in the gastric cancer cells by western blot analysis and luciferase activity assays." (PMID 25295122, 2014). "High Bmi1 expression levels were detected in 45% (24/53) of gastric cancer samples and 54% (20/37) of colon cancer samples." (PMID 24312366, 2013). "Recently, high expression of BMI1 was observed both in gastric cancer cell lines and gastric tumors." (PMID 22539939, 2012). "Overexpression of BMI1 was found to be correlated with advanced clinical stage and lymph node metastasis in gastric cancer patients." (PMID 22539939, 2012). "Studies have unraveled many aberrantly expressed genes in gastric cancer including BMI1, COX-2, HER3, RKIP and STAT3, SPARC and HER2, which make risk assessment of gastric cancer patients more accurately." (PMID 21933426, 2011). "The expression of Bmi-1 and Mel-18 was correlated with gastric cancer progress, advanced gastric cancer more likely expressed higher Bmi-1 and lower Mel-18." (PMID 21059209, 2010). "It is possible to list Bmi-1 and Mel-18 as biomarkers for predicting the prognosis of gastric cancer." (PMID 21059209, 2010). "In the current study we demonstrated that neoplastic cells in gastric cancer can't normally express Bmi-1 and Mel-18." (PMID 21059209, 2010). "Here, we show that BMI1 is overexpressed in gastric cancer cell lines and gastric tumors, and its expression correlated with advanced clinical stage, lymph node metastasis, and poor prognosis." (PMID 20170541, 2010). "In summary, our studies suggest that Mel-18 and BMI1 play important but opposite roles in the tumorigenesis, progression and metastasis during gastric cancer development; BMI1 acts as an oncogene, while Mel-18 functions as a tumor suppressor." (PMID 20170541, 2010). "Recently we reported that Bmi-1 was overexpressed in gastric cancer cell lines and gastric tumors and plays an important role in the carcinogenesis and progression of gastric cancer." (PMID 20723236, 2010). "Overexpression of BMI1 in gastric cancer has been previously reported, however the potential mechanism of its overexpression remained unclear." (PMID 20170541, 2010). "In the context of gastric cancer, BMI1 acts as an oncogene and Mel-18 functions as a tumor suppressor via downregulation of BMI1." (PMID 20170541, 2010). "This research is the first time to study the correlation between Mel-18 or Bmi-1 expression at mRNA level and clinicopathological characteristics of gastric cancer by quantitative method." (PMID 21059209, 2010).
gastric cancer (continued). "It has been reported that BMI1 is overexpressed in gastric cancer cells and is an independent prognosis factor." (PMID 20170541, 2010). "It has been reported that Bmi-1 is overexpressed in gastric cancer and is an independent prognosis factor." (PMID 21059209, 2010). "In this study, we characterized the expression profile of Mel-18 and Bmi-1, and their clinical significance in gastric cancer." (PMID 21059209, 2010). "The expression of Mel-18, BMI1, pAkt, and p16; and the correlations between these proteins in gastric cancer tissues and normal gastric mucosa tissues." (PMID 20170541, 2010). "Here, we examine the expression of Mel-18 and Bmi-1 at mRNA level by using QRT-PCR method in a series of gastric cancer, and evaluate the correlation between Mel-18 and Bmi-1 expression levels." (PMID 21059209, 2010). "Our in vitro study also showed that overexpression of Mel-18, and knockdown of BMI1 expression, inhibit the ability of migration in gastric cancer cells." (PMID 20170541, 2010). "Recently we found that Bmi-1 plays an important role in the carcinogenesis and progression of gastric cancer and acts as an oncogene." (PMID 20723236, 2010). "Downregulation of BMI1 was also accompanied by decreased transformed phenotype and migration in both p16- positive and p16-negative gastric cancer cell lines." (PMID 20170541, 2010). "Here we confirmed previous observation that BMI1 is overexpressed in gastric cancer cell lines and gastric tumors and that BMI1 overexpression correlates with poor prognosis." (PMID 20170541, 2010). "The expression of Mel-18 and Bmi-1 in a series of 71 gastric cancer tissues and paired normal mucosal tissues distant from the tumorous lesion was assayed by quantitative real time RT-PCR." (PMID 21059209, 2010). "We investigate the expression and clinicopathological roles of Mel-18 and Bmi-1 mRNA in gastric cancer." (PMID 21059209, 2010). "We have found that regulation of AKT/PKB pathway is another important mechanism for Bmi-1 in breast and gastric cancers." (PMID 20723236, 2010). "In another study, Bmi-1 expression was closely related with the Lauren's and Borrmann's classification and clinical stage in gastric cancer." (PMID 21059209, 2010). "In addition to c-Myc, E2F1 also activates BMI1 expression in neuroblastoma and gastric cancer cells." (PMID 36362068, 2022). "Our results, together with those of others, suggest that Bmi-1 could be used as a new target in the development of new therapies for gastric cancer." (PMID 35415241, 2022). "Essentially, silencing CCAT1 could downregulate BMI1 in gastric cancer, whereas miR-218 suppresses the BMI1 expression in hepatocellular carcinoma." (PMID 35261819, 2022). "Several studies of patients with gastric cancer have suggested that Bmi-1 may serve as an independent prognostic factor in predicting the survival of patients with gastric cancer." (PMID 35415241, 2022). "In addition, CD44, Wnt2, Bmi1, Notch1, Oct4, Sox2, Nanog, C-mys, ABCG2, CXCR4 and other “stemness associated genes” are highly expressed in the CD44+ gastric cancer cell population." (PMID 36316684, 2022). "In vitro assay illustrated that E2F1 could regulate the expression of stemness-associated genes, such as BMI1, OCT4, Nanog, and CD44, and maintain the tumor spheroid formation ability of gastric cancer cells." (PMID 33986804, 2021). "Co-expression of USP22 and BMI1 could accelerate tumor development, stemness and predict therapy failure in gastric carcinoma." (PMID 34753387, 2021). "Similarly, the miR-27a inhibitor and miR-155 inhibitor weakened the effects of Bmi-1 overexpression on migration, invasion and drug resistance in gastric cancer cells." (PMID 32580736, 2020). "It has also been shown that the increased stability of BMI1 induces CSC populations by inducing the expression of stemness associated genes such as CD133, SOX2, OCT4 and NANOG and thereby, favor the progression of gastric cancer." (PMID 34660907, 2020).
gastric cancer (continued). "Similarly, AAV vector-mediated inhibition of Bmi-1 driven by the expression of a Bmi-1 shRNA suppressed tumor growth and stem cell-like properties of gastric cancer cells in vitro and in vivo." (PMID 32674264, 2020). "Besides, Bmi1 upregulates miR-21 and miR-34a by activating Akt-NF-κB pathway to regulate stem cell-like properties of gastric cancer cells." (PMID 31171917, 2019). "Previously, we reported that BMI1, another member of the PcG family, could regulate stem cell-like properties of gastric cancer cells through the upregulation of miR-21 via AKT-NF-κB pathway." (PMID 29422082, 2018). "We previously reported that BMI1 could regulate stem cell properties of gastric cancer through the upregulation of miR-21 by activating AKT-NF-κB pathway." (PMID 29422082, 2018). "In addition, miR-128 can inhibit gastric cancer migration, invasion, proliferation, and metastasis by targeting Bmi-1 in vivo and in vitro." (PMID 28424413, 2017). "Furthermore, we found that overexpression of USP22 stabilized the BMI1 protein in gastric cancer cells." (PMID 28415621, 2017). "It has been reported that high expression of Bmi-1 could significantly lead to a poor OS in gastric cancer patients." (PMID 28220856, 2017). "Additionally, overexpression of miR-128 inhibited gastric cancer cell migration, invasion, and proliferation by targeting Bmi-1 in vitro and in vivo." (PMID 28424413, 2017). "We also documented, with receiver operating characteristic curves and Kaplan-Meier survival analysis, that miR-128 and Bmi-1 may be useful markers for diagnosing and estimating the prognosis of gastric cancer patients." (PMID 28424413, 2017). "Altogether, these results demonstrated that miR-128 could inhibit EMT via Bmi-1 through the PI3K/AKT pathway in gastric cancer cells." (PMID 28424413, 2017). "Because Bmi-1 is a direct target gene of miR-128, we inferred that miR-128 could determine the epithelial phenotype of gastric cancer by regulating Bmi-1." (PMID 28424413, 2017). "Thus, we conclude that miR-128 inhibits gastric cancer cell migration, invasion, and proliferation by targeting Bmi-1." (PMID 28424413, 2017). "Furthermore, we also found that Bmi-1 overexpression increased migration ability and drug resistance in gastric cancer cells in vitro, which are also characteristics of CSCs." (PMID 27009837, 2016). "The favorable outcome of gastric cancer patients with high levels of Bmi-1 may be due to the fact that these gastric tumor cells are highly sensitive to chemotherapy treatment while patients with low Bmi-1 level are less sensitive." (PMID 26894855, 2016). "In gastric cancer tissues, miR-21 had a significantly positive correlation with Bmi-1 expression." (PMID 27644439, 2016). "B-cell specific moloney leukemia virus insertion site 1 (Bmi-1) gene plays important roles in gastric cancer, but the epigenetic regulatory mechanism by microRNA (miRNA) and the functional significance of Bmi-1 inhibition in gastric cancer remains elusive." (PMID 26894855, 2016). "We intended to clarify whether Bmi-1 downstream miRNAs is involved in the regulation of stemness in gastric cancer cells." (PMID 27644439, 2016). "Our previous findings also showed that Bmi-1 acts as an oncogene in gastric cancer and an independent prognostic factor in gastric cancer tissues, suggesting it can also be a good therapeutic target for gastric cancer." (PMID 27009837, 2016). "Therefore, we evaluated the role of Bmi-1 in mediating the proliferation of a gastric cancer cell lines." (PMID 26894855, 2016). "So, we conducted ChIP test to verify whether Bmi-1 may bind to the PTEN promoter in gastric cancer cells." (PMID 27644439, 2016). "We firstly explored the role of Bmi-1 in regulating stem cell-like features in gastric cancer." (PMID 27644439, 2016).